COL1A1 (collagen type I alpha 1 chain)
Diseases named in the same sentence as COL1A1 in open-access papers (continued):
Sharing a sentence is not in itself a finding about the gene and the disease.
keloid (30 papers, 2012 to 2026). An irregularly shaped, elevated mark on the skin caused by deposits of excessive amounts of collagen during wound healing. "qPCR and Western blotting analysis showed that overexpression of ALKBH5 notably promoted the mRNA and protein levels of α‐SMA and COL1A1 in keloid fibroblasts." (PMID 40214031, 2025). "And the protein levels of α‐SMA and COL1A1 were found to be upregulated in the skin tissues of keloid mice, and which were restored with the intervention of sh‐RCN1." (PMID 40214031, 2025). "Our immunostaining results also indicated that TEM1 expression was significantly higher in hypertrophic scars and keloids than in normal skin, as well as being associated with fibroblast activation markers such as α-SMA, COL1A1, and FN1." (PMID 38254097, 2024). "Consistently, the IHC staining showed that COL1A1 diffused in keloid skin dermis was significantly decreased in siZyxin group." (PMID 37215989, 2023). "Among them, COL1A1 and COL1A2 encode type I collagen and COL3A1 encodes type III collagen, the major components of the extracellular matrix in keloid tissue." (PMID 35872873, 2022). "It was downregulated in keloid and can negatively regulate the expression of COL1A1, COL1A2, COL3A1, COL5A1, and COL5A2." (PMID 35872873, 2022). "Previous studies have confirmed that miR-29a-3p was significantly downregulated in keloid tissues and fibroblasts and can regulate the proliferation, apoptosis, migration, and invasion of KFs by targeting COL1A1 and COL3A1." (PMID 35872873, 2022). "The diagnostic value of COL1A1, COL1A2, COL3A1, COL5A1, and COL5A2 between keloid and different control tissue was evaluated by different datasets." (PMID 35872873, 2022). "The deep keloid model had a thicker dermis and increased COL1A1 expression, while the superficial keloid model only showed an increased wound area after grafting." (PMID 30370495, 2018). "After 12 hours of TGF-β1 treatment, the expression of COL1A1 was increase in keloid fibroblasts, while in normal fibroblasts the increase was observed after 48 hours." (PMID 27897224, 2016). "Notably, the Fibroblast2 cluster included cells with higher levels of COL1A1 expression, and there were increased cell numbers in the Fibroblast2 cluster in keloids compared with normal tissue." (PMID 40742741, 2025). "TGF-β and collagen type I alpha 1 (COL1A1) are mediators of fibrosis in keloid patients." (PMID 37524866, 2023). "Compared with normal skin, type I and III collagen deposition in keloid tissue increased significantly, and previous studies have confirmed that miR-29a-3p can regulate the biological behavior of KFs by directly targeting COL1A1 and COL3A1." (PMID 35872873, 2022). "They determined that only 25 common dysregulated genes were in keloids in 7 studies where collagen, type I, alpha 1 (COL1A1); collagen, type I, alpha 2 (COL1A2); collagen, type V, alpha 2 (COL5A2); and collagen, type VI, alpha 1 (COL6A1) were systematically upregulated." (PMID 33860039, 2021). "The in vitro assay showed that lncRNA H19 might facilitate proliferation and metastasis of fibroblasts by modifying downstream miR-29a and COL1A1, engaging in the development of keloid-targeted treatments." (PMID 33243301, 2020). "Additionally, EDN1 and NTF3 exhibited high correlations with fibrosis markers (COL1A1, TGFB1), inflammatory cytokines (IL6, TNFA), and immune cell infiltration (e.g., activated mast cells), suggesting their central regulatory roles in keloid-associated fibrosis and inflammation." (PMID 40051702, 2025). "In agreement with our interactome, regulation of ELN, COL5A2, FSTL1 and COL1A1 was demonstrated experimentally using a miR-29b mimic and antagomir in primary human skin fibroblasts and other models in the context of treatment of keloid formation and fibroplasia using miR-29b mimic Remlarsen." (PMID 39883689, 2025).
keloid (continued). "Moreover, in keloid tissue, a positive correlation was noted between the level of Foxp3 expression and the level of encoding type III collagen (type III collagen alpha 1, COL3A1) expression and the COL3A1/type I collagen alpha 1 (COL1A1) ratio." (PMID 37867188, 2023). "Interestingly, according to studies, in keloid, one of the benign skin tumors, ADSCs could reduce the expression of COL1A1 in keloid fibroblasts and deposition of collagen in keloid tissue ex vivo." (PMID 34362454, 2021). "Among the genes enriched in the extracellular region pathway, 24 genes including COL1A1, COL1A2, and COL4A1 were significantly upregulated in keloid tissues." (PMID 41562114, 2025). "RSL3 injection into keloid tissue dramatically decreased the mRNA levels of fibrotic genes, such as α-SMA, COL1A1, COL1A2, COL3A1, and FN1, and downregulated the ECM contents, according to qPCR analysis and the Sircol test." (PMID 40860189, 2025). "Isolated deep lesional fibroblasts display elevated expressions of collagen type I alpha 1 chain (COL1A1), consistent with our findings where COL1A1, COL1A2, COL4A1, and COL5A1 were prominently upregulated in keloid tissues." (PMID 41562114, 2025). "We clustered collagen gene expression in keloids and lymphedema and found that keloid tissue tended to have higher expression of COL3A1, COL1A2, COL1A1, COL6A1, and COL5A1 than did the ML and SL groups." (PMID 40742741, 2025). "In keloid tissues, TEM1 was found to co-localize with several fibroblast-activated markers, including α-SMA, COL1A1, and FN1, supporting its expression in fibroblasts within the scar tissue." (PMID 38254097, 2024). "We demonstrated, in scRNA-seq datasets of hypertrophic scars and keloids, that the TEM1 gene was mostly co-expressed with the COL1A1 and FN1 genes in a specific and major sub-population of fibroblasts." (PMID 38254097, 2024). "ScRNA-seq analysis identified consistent expression patterns for TEM1, ACTA2, COL1A1, FN1, TGFBR1, and TGFBR2 in distinct fibroblast subsets of both keloids and hypertrophic scars." (PMID 38254097, 2024). "The transcriptomic levels of TEM1, as well as of COL1A1 and FN1, were predominantly upregulated in the Fs1 subgroup which comprised almost half of all keloid fibroblasts." (PMID 38254097, 2024). "Increased expression of COL1A1, PAI-1 and urokinase receptor was reported in heterotopic keloid implants." (PMID 35529910, 2022). "Genes involved in extracellular matrix formation including COL1A1, COL3A1, POSTN, COL1A2, FN1, and ASPN were significantly upregulated in keloid compared to the normal skins." (PMID 35990663, 2022). "In our study, the results of ENCORI prediction and RT-qPCR showed that miR-29a-3p can regulate the expression of COL1A1, COL1A2, COL3A1, COL5A1, and COL5A2, and these target genes were closely related to the development of keloid." (PMID 35872873, 2022). "This decrease in CRIF1 abundance led to decrease in cell proliferation, migration, and mRNA expressions of COL1A1 and COL3A1, all of which play an integral role in keloid formation." (PMID 33436666, 2021). "Lipo-PGE1 also decreased COL1A1, COL1A2, and COL3A1 mRNA expression and the total soluble collagen level in keloid fibroblasts." (PMID 28644845, 2017). "In contrast, COL1A1, COL1A2, and POSTN expression levels were significantly increased in wounded keloid ESS." (PMID 22536458, 2012). "For instance, while pirfenidone suppresses collagen (COL1A1) mRNA expression in lung fibroblasts and myometrial cells, this effect is not observed in keloid or dermal fibroblasts, suggesting tissue-specific responses to the drug." (PMID 40843770, 2025). "In addition, the mRNA expression levels of ECM genes including COL1A1 and FN1 as well as that of TGF-β-related genes such as TGFB1, TGFBR1, and TGFBR2 were highly expressed in keloids." (PMID 38254097, 2024).
keloid (continued). "When the diagnostic value of these key genes were evaluated between the normal skin from keloid-prone or normal individuals (GSE113619), the AUC values of COL1A1, COL1A2, COL3A1, COL5A1, and COL5A2 in keloid were 0.650, 0.625, 0.575, 0.525, and 0.450, respectively." (PMID 35872873, 2022). "Downregulation of miR-196a may be one of the mechanisms by which collagens are highly deposited in keloid tissue, as the reporter analysis showed miR-196a upregulation reduced the expression of collagen in KFs through binding to the 3′UTR of COL1A1 and COL3A1." (PMID 33243301, 2020). "In the PTB siRNA group, the expressions of COL3A1 and FN1 but not COL1A1 significantly decreased in keloid xenograft tissues." (PMID 27897224, 2016). "In keloids, the proportion of mesenchymal fibroblasts is significantly higher than in normal scars, and these cells express higher levels of ossification‐related genes such as cartilage oligomeric matrix protein (POSTN) and collagen‐related genes like type I collagen α1 (COL1A1)." (PMID 39902627, 2025). "In vitro phenotypic assessment using the intact C1Q complex showed that C1Q increased ACTA2 expression in primary keloid fibroblasts, whereas RAP attenuated this effect; COL1A1 and POSTN showed no consistent induction." (PMID 42278663, 2026). "First, the Western blotting results of keloids and the adjacent normal skin from the same subjects revealed that the expression levels of STAT3, COL1A1, and FN1 were increased in keloids relative to those in normal skin." (PMID 35628356, 2022).
melanoma (30 papers, 2015 to 2025). A malignant, usually aggressive tumor composed of atypical, neoplastic melanocytes. "Ectopic WT-Bmal1 and dHLH-Bmal1 increased genes associated with mesenchymal melanoma state, such as Sox9, Fn1, Col1a1, Prrx2, Klf4, Snai2, Twist2, Lmo1 and Axl31." (PMID 38245503, 2024). "Many of these downregulated proteomic cargoes in melanoma sEVs, including collagens (COL1A1, COL3A1, COL6A1–A3, and COL14A1), matrix-associated proteoglycans (DCN, LUM, FMOD, OGN, and PRELP), and structural regulators (TNXB and PCOLCE), are key components of ECM organization and tensile strength." (PMID 41271007, 2025). "For example, BCAN is significantly differentially expressed in IFN-treated melanoma, and promoter mutations of TERT in melanoma and COL1A1 promote melanoma invasion, among others." (PMID 40350499, 2025). "The up‐regulation of COL1A1 and MPZ caused by EGR3 overexpression was validated in both A375 and B16‐F10 melanoma cell lines." (PMID 38973154, 2024). "Significantly higher COL1A1 protein levels were observed in ANH than in DNH or melanoma cells of MLiM." (PMID 39496484, 2024). "Four region-specific marker genes (PMEL for melanoma region, COL1A1 for stroma region, CXCL10 for lymphoid tissue 2, and MS4A1 for lymphoid tissue 1) were identified from the ST data to demonstrate the accuracy of imputed expression." (PMID 39402626, 2024). "In conclusion, ANH from MLiM showed an upregulation in CXCR4 and COL1A1/2, while melanoma cells of MLiM showed a significant upregulation in TNF." (PMID 39496484, 2024). "The experiments demonstrated the specificity of MLiM cell supernatant to induce CXCR4 and COL1A1/2 compared with metastatic cell lines of different cancer types as well as different melanoma organ metastasis." (PMID 39496484, 2024). "Intriguingly, mRNA levels of COL1A1 and COL1A2, coding for collagen type 1, which is most abundant of the collagens, were also linked with PTGES in patients with melanoma." (PMID 37529399, 2023). "The results showed that the alternations of COL1A1 are related to the better prognosis of melanoma with overall survival (p = 0.0158), progression-free survival (p = 0.0385), and disease-specific survival (p = 0.0361)." (PMID 34395525, 2021). "In clinical melanoma samples, the upregulation of COL1A1 was negatively correlated with disease-free survival." (PMID 34252359, 2021). "Consistent with the literature, the PDGFR and Col1a1 canonical CAF markers continue to be broadly very important in melanoma-however, this could be due to initial clustering based on Col1a1 in many cases." (PMID 38525245, 2024). "For each expected cell type in each region, we selected its marker genes from existing literature, which included PMEL for malignant cells in melanoma regions, COL1A1 for fibroblast in stroma regions, MS4A1 for B cells and CD14 for macrophage in lymphoid tissues." (PMID 39402626, 2024). "Transcriptome sequencing of EGR3‐expressing A375 melanoma cells revealed significant up‐regulation of multiple genes associated with the extracellular matrix (ECM), such as COL1A1, COL5A3, and FN1, thereby confirming the regulatory role of EGR3 in the remodeling of the extracellular space." (PMID 38973154, 2024). "Interestingly, several of these AhR‐associated genes have been involved in the aggressiveness of melanoma or other cancers and have been associated with a poor prognosis (ABCG2, COL1A1, COL6A1, COL6A2, TGFBI)." (PMID 36305167, 2022). "First, high level and activity of AhR mediates the invasive/dedifferentiated phenotype of melanoma through the direct regulation of the expression of many genes involved in invasion (COL1A1, COL6A1, COL6A2, CYR61, STC2...) and dedifferentiation phenotypes (CCL2, NTM, NUAK2, SOX9, ABCG2...)." (PMID 36305167, 2022). "Importantly, COL1A1 expression correlated strongly with melanoma invasion, (Sk-mel-28 p = 0.02, R = 0.32)." (PMID 33980846, 2021). "Notably, high expression of COL1A1 also correlated with poor prognosis in patients with melanoma." (PMID 35654839, 2022).
melanoma (continued). "To further explore the clinical significance of collagen‐mediated immune exclusion, we assessed the relationship between COL1A1 expression, CD8+ T cell infiltration, and patient survival in melanoma." (PMID 40847444, 2025). "A smaller tissue from patient ID 9561, collected in 2008, had four clusters, including melanoma (PMEL, TYRP1), immune cells (TMSB4X, IL32), keratinocytes (KRT10, KRT1, DSG1), and fibroblast areas (COL1A2, COL1A1, DCN)." (PMID 39846232, 2025). "A positive correlation between the expressions of COL1A1 and MPZ with EGR3 expression in melanoma patients was also observed." (PMID 38973154, 2024). "In NGDSP analysis adjacent normal hepatocytes (ANH) had higher CXCR4 and COL1A1/2 levels than distant normal hepatocytes (DNH), while melanoma cells had higher TNF‐α levels." (PMID 39496484, 2024). "We confirmed UVR-damaged fibroblasts persistently upregulate collagen-cleaving matrix metalloprotein-1 (MMP1) expression, reducing local collagen (COL1A1), and COL1A1 degradation by MMP1 decreased melanoma invasion." (PMID 33980846, 2021). "THBS2, COL1A1, ADAMTS2 resulted significantly up-regulated in the group of melanomas compared to melanocytomas (P < 0.05, Mann–Whitney)." (PMID 28743863, 2017). "By comparing gene expression in the primary and wound metastatic lesion of the melanoma patient, we found that among genes related to wound healing, genes of ECM proteins, including POSTN, COL1A1, and FN1, were overexpressed in the wound metastatic lesion." (PMID 26083413, 2015). "In addition, we identified Mesenchyme (COL1A1+), Endothelium (SOX18+, KDR+), proliferating cells (TOP2A+, MKI67+), and some off‐target cells; Glial (MSX1+, SOX2+), Melanoma (PMEL+, PLP1+), and Neuron (DLL3, HES6)." (PMID 35322595, 2022). "However, COL1A1 and COL1A2 were both strongly overexpressed in the melanomas compared to melanocytomas, in agreement with the study from Van Kempen." (PMID 28743863, 2017). "The non-immune cell clusters were made up of melanoma cells (MLANA, PMEL, MITF, DCT), endothelial cells (VWF, PECAM1) and fibroblast cells (COL1A1, COL3A1)." (PMID 36433984, 2022).
steatosis (28 papers, 2018 to 2025). Increased lipid within the cytoplasm of cells. "The high-risk PNPLA3 GG variant LAMPS demonstrated increased steatosis, pro-inflammatory cytokine secretion, stellate cell activation, and secretion of the pro-fibrotic marker COL1A1, consistent with the clinical characterization of this polymorphism." (PMID 39324073, 2024). "To show a causal role of steatosis induction on fibrosis development and hepatic stellate cell activation, we measured levels of collagen I (COL1A1)." (PMID 30986904, 2019). "In addition, we observed genotype-specific differences in response to drug treatment as resmetirom demonstrated greater efficacy in the PNPLA3 wild-type CC LAMPS than that in the GG variant in the reduction of steatosis, stellate cell activation, and the secretion of marker COL1A1." (PMID 39324073, 2024). "We also found increased levels of triglycerides, alanine aminotransferase (ALT), Ccr2, and Col1a1 mRNAs, which indicate steatosis, hepatocellular damage, liver inflammation, and collagen deposition." (PMID 38817615, 2024). "Consistently, histological analysis of DS liver reveals increased fibrosis and steatosis, as showed by Col1a1 increased expression, indicative of potential progression to liver cirrhosis." (PMID 38942607, 2024). "For example, the downregulation of CD36 expression in the liver by MicroRNA-29 led to an attenuation of high fat diet induced steatosis along with a reduction in the expression of fibrotic markers including Col1a1." (PMID 38098035, 2023). "In two different NASH mouse obesity models, an atherogenic diet model and ob/ob mice, chronic treatment with liraglutide reduced body weight, lowered steatosis scores and inhibited fibrosis (through a decreased col1a1)." (PMID 33324348, 2020). "Individual reductions in Col1a1 fractional area closely correlated to corresponding improvements in steatosis and galectin-3%-area." (PMID 31227742, 2019). "The individual reduction in the proportionate area of Col1a1 was closely correlated with improvements in steatosis and inflammation, illustrating a highly consistent within-subject effect on all three histological endpoints." (PMID 31227742, 2019). "Therefore, the upregulation of Il-6, Tnf, Mapk13, and Col1a1 pathways under KD at TN likely drives steatosis progression to MASH and fibrosis." (PMID 40864559, 2025). "We observed genotype-specific differences in response to resmetirom consistent with this, demonstrating that steatosis, stellate cell activation, and secretion of the pro-fibrotic marker COL1A1 were significantly reduced in the PNPLA3 wild-type LAMPS compared to the GG LAMPS." (PMID 39324073, 2024). "Moreover, the accumulated intrahepatic DAG/TAG species correlate to increased expression of genes and genetic pathways associated with steatosis-to-MASH transition, including Col1a1 and cell adhesion/ECM remodeling pathways." (PMID 39405118, 2024). "Interestingly, we found that the COL1A1 levels were decreased after steatosis prevention by liraglutide or elafibranor incubations." (PMID 30986904, 2019). "The best model included eight predictor variables, most of which are related to liver histology (steatosis score, lobular inflammation, % Col1a1, % galectin‐3, fibrosis stage), in addition to liver tissue triglycerides (TG), plasma cholesterol (TC), and expression of the Gpnmb‐Mm01328587 gene." (PMID 31599067, 2019). "Previously, collagen genes, such as collagen type 1 alpha 1 chain (COL1A1), were shown to be consistently up-regulated with MASLD progression from steatosis to fibrosis." (PMID 38474754, 2024). "This was accompanied by steatosis, increased Bax/Bcl-2 ratio, and overexpression of p-SAPK/JNK, Tgfβ1, Map3k14, and Col1a1 in the liver." (PMID 34663892, 2022). "Analyses were conducted on the following outcomes: steatosis, ballooning hepatocytes, NAS-index, fibrosis, IL-8, MCP-1, TNF-α, α-sma, Col1a1, TGF-β, CYP7A1, HC and HT." (PMID 32882802, 2020).